ZNF85 (zinc finger protein 85)
Description:
May be a transcriptional repressor.
Synonyms: HPF4; HTF1
Tractability: PROTAC: ubiquitination databases record sites on it.
Gene: Protein-coding gene on chromosome 19 (20,923,222 to 20,950,697, forward strand). Ensembl gene ENSG00000105750.
Subcellular location: Nucleus
Subcellular location (Human Protein Atlas): Nucleoplasm
Gene Ontology:
Molecular function: DNA-binding transcription repressor activity, RNA polymerase II-specific; RNA polymerase II cis-regulatory region sequence-specific DNA binding; DNA-binding transcription factor activity, RNA polymerase II-specific
Biological process: regulation of DNA-templated transcription; negative regulation of transcription by RNA polymerase II; regulation of transcription by RNA polymerase II
Cellular component: nucleoplasm; nucleus
Genetic constraint (gnomAD): Loss-of-function variants: 42 observed, 50.16 expected, observed/expected ratio (o/e) 0.84, 90% interval 0.65 to 1.08. The upper end of that interval is the gene's LOEUF score, 1.08, which puts it in group 4 of 6, group 1 being the genes least tolerant of losing a copy. Missense variants: 731 observed, 682.41 expected, observed/expected ratio (o/e) 1.07, 90% interval 1.01 to 1.14. Synonymous variants: 222 observed, 222.73 expected, observed/expected ratio (o/e) 1, 90% interval 0.89 to 1.11.
Homologues: Orthologues: chimpanzee ZNF85 (98% identical), mouse Zfp738 (54% identical), mouse Zfp595 (52% identical), mouse Zfp457 (52% identical), rat AABR07009105.1 (39% identical), mouse Zfp953 (27% identical). Paralogues in human: ZNF681 (75% identical), ZNF724 (75% identical), ZNF254 (70% identical), ZNF708 (70% identical), ZNF726 (69% identical), ZNF43 (68% identical), ZNF728 (67% identical), ZNF493 (67% identical), ZNF429 (66% identical), ZNF93 (66% identical), ZNF676 (64% identical), ZNF90 (61% identical), and 164 more.
Diseases named in the same sentence as ZNF85 in open-access papers:
ZNF85 is named in the same sentence as 13 diseases in open-access papers, as found by Europe PMC text mining. Sharing a sentence is not in itself a finding about the gene and the disease. The quoted sentences say what the papers report.
breast tumors (1 paper, 2023). "In their analysis, the genomic region harboring ZNF714 (and other genes, including its closest neighbors: ZNF85, ZNF430, ZNF431, ZNF708) was found to undergo copy number gains in estrogen-negative (ER-) breast tumors as compared to ER+ tumors." (PMID 37958512, 2023).
glioma (1 paper, 2023). A benign or malignant brain and spinal cord tumor that arises from glial cells (astrocytes, oligodendrocytes, ependymal cells). "TFBS for factors such as ZNF85, PO3F1, HX36, SOX1, and SOX10 were found in genes overexpressed in GII gliomas." (PMID 36850002, 2023).
preeclampsia (1 paper, 2024). Preeclampsia is a hypertensive disorder of pregnancy that is characterized by new-onset hypertension with proteinuria presenting after 20 weeks of gestation, and depending on mild or severe forms may initially present with severe headache, visual disturbances, and hyperreflexia. "Differentially expressed ZNF85 is involved in the top 10 GO terms, including DNA and ion bindings, between preeclampsia cases and controls." (PMID 38666946, 2024).
ZNF85 also shares sentences with these, for which no sentence is quoted: Thrombocytopenia (4 papers); thrombosis (3); cancer (2); endotoxemia (1); glioblastoma (1); malaria (1); myocardial infarction (1); pulmonary embolism (1); Sepsis (1); Stroke (1).